BRCA1 (BRCA1 DNA repair associated)
Diseases named in the same sentence as BRCA1 in open-access papers (continued):
Sharing a sentence is not in itself a finding about the gene and the disease.
cancer (continued). "Notwithstanding the importance of PARP-1 in numerous pathways that govern genome integrity, the effective killing of HR-deficient BRCA1/2-mutated cancer cells by PARP inhibitors (PARPi) has been the basis for the development of therapies targeting breast and ovarian tumors." (PMID 37609662, 2023). "Circulating microRNAs may be used to identify BRCA1/2 mutations in patients of high risk of cancer, offering an opportunity to reduce screening costs." (PMID 37291133, 2023). "A meta-analysis and systematic review that attempted to compare responses to PARP inhibitors between germline and somatic BRCA1/BRCA2 mutations across cancer types concluded that the drugs appear to be equally effective but noted heterogeneity and possible publication bias." (PMID 36975505, 2023). "However, some studies using a targeted sequencing approach have discovered a higher proportion (62–73%) of PVs in other cancer susceptibility genes other than BRCA1/2, with nearly equal contribution to hereditary BC." (PMID 37791908, 2023). "Poly ADP‐ribose polymerase inhibitor (PARPi) is a potentially synthetic lethal effect agent for the therapy of cancers characterized by specific DNA‐repair defects, such as tumor cells that contain BRCA1 and/or BRCA2 (BRCA1/2) mutations and present defects in homologous recombination repair." (PMID 35871395, 2023). "From the therapeutic perspective, cancer cells with BRCA1/2 mutations are very sensitive to poly (ADP-ribose) polymerase (PARP) inhibitors because PARP inhibitors cause an increase in DNA single-strand breaks, which are then converted to irreparable toxic DNA DSBs in those cells during replication." (PMID 38069409, 2023). "Moreover, cancer-associated mutations in the BRCT domains of BRCA1 and BARD1 abolish their interactions with pre-rRNA." (PMID 37789001, 2023). "The most important genetic markers of breast cancer are defined as breast cancer gene 1 (BRCA1) and breast cancer gene 2 (BRCA2) mutation genes, which are the most powerful predictive tools to identify patients suffering from breast and ovarian cancer with a 40%–80% risk of developing cancer." (PMID 37213283, 2023). "Notably, fibroblasts from BRCA1+/mut carriers exhibit a phenotype resembling cancer-associated fibroblasts (CAF) even at the precancerous stage, commonly referred to as the “pre-CAF” phenotype." (PMID 38275383, 2023). "Cancer risk management: This module offers generic information on how testing results can inform prevention and screening for cancers known to be associated with BRCA1/BRCA2-associated HBOC." (PMID 37760455, 2023). "Based on these data, it is plausible to argue that, similar to germline BRCA1 mutations, constitutional BRCA1-methylation may likewise increase the risk of cancer formation in BRCA1-carrying women." (PMID 37240365, 2023). "Several PARP inhibitors have already been approved for BRCA1/2 mutated cancers." (PMID 37735513, 2023). "Constitutional BRCA1-methylation is a cancer risk factor for breast (BC) and ovarian (OC) cancer." (PMID 37240365, 2023). "Therefore, BRCA1-deficient cancer cells need to reduce the protein level of RNF168 to maintain a certain HR level in order to ensure survival." (PMID 36771081, 2023). "Therefore, cancer-unaffected members of families with a known BRCA1/2 pathogenic variant are generally offered genetic counseling and testing." (PMID 37185387, 2023). "Thus, it became evident that while mutations causing truncated BRCA1 forms are associated with cancer predisposition in humans, there is an inherent selection favoring amino acid-altering substitutions in this gene." (PMID 38275383, 2023). "In cancers with BRCA1/BRCA2 mutations or other defects in HR repair, cells are dependent on poly-adenosyl-ribose polymerase (PARP) enzymes to carry repair of their damaged DNA and are thus prone to apoptosis if the enzyme is inhibited by PARP inhibitors, a concept known as synthetic lethality." (PMID 36975505, 2023).
cancer (continued). "The sensitising effect of BRCA1/2 deficiency might thus explain the associated survival differences among cancer types." (PMID 36883553, 2023). "Thus, PARP inhibitors (PARPi) are effective targeting agents by competitively inhibiting the activity of PARP in cancers with BRCA1/BRCA2 mutation." (PMID 36694209, 2023). "Cancers related to BRCA1/2 mutations comprise about 5–7% of BC and 20–25% of OC cases." (PMID 37445860, 2023). "In this small subgroup, BRCA1/2 mutations were often accompanied by productive rearrangements in ascites (one-sided Mann-Whitney p = 0.07), which is consistent with reports that BRCA1/2-deficient cancers have an increased burden of mutations and neoantigens." (PMID 36607962, 2023). "Our findings support the importance of genetic risk factors in the etiology of BC in Tanzanian population and furthermore, suggest the absolute necessity of improving genetic cancer risk assessment such as BRCA1/2 genetic testing and counseling services for BC patients in Tanzania." (PMID 35908255, 2023). "However, cancer cells, particularly those with mutations in certain DNA repair genes, such as BRCA1 or BRCA2, are more dependent on PARP (synthetic lethality)." (PMID 37296748, 2023). "Therefore, cancer cells harboring mutated BRCA1 or BRCA2 are particularly sensitive to PARP inhibition." (PMID 37510250, 2023). "Based on this mechanism of action, combinatorial therapy with both USP1 and PARP inhibitors may have clinical efficacy in BRCA1-deficient cancers with acquired resistance to PARP inhibitors." (PMID 38201233, 2023). "However, using PARP1 knockout cells, Hopkins and colleagues showed that PARP1 is the primary target in causing cytotoxicity in BRCA1/2 mutant cancers." (PMID 37035242, 2023). "To date, the use of PARP inhibitors has been limited to the treatment of BRCA1-deficient cancers." (PMID 38201233, 2023). "Therefore, cell viability and RAD52 foci formation in BRCA1/2-deficient cancer cells are often performed to indirectly demonstrate target engagement and synthetic lethality." (PMID 36980703, 2023). "However, the majority of studies reporting the association of the BRCA1 constitutional epimutation with cancer risk also show that if constitutional methylation is present in blood samples, it is present at a very low level." (PMID 37752189, 2023). "Mutations in the BRCA1 gene are closely associated with cancer formation." (PMID 37509303, 2023). "PARP inhibitors serve several roles in cancer treatment, including sensitization to chemotherapy and radiotherapy, synthetic lethality in tumors from patients with hereditary mutations in BRCA1/2 genes, and leveraging of supposed “BRCA-like” defects and defects in DNA repair." (PMID 36999995, 2023). "Our findings question whether mosaic constitutional methylation of other tumor suppressor genes, beyond BRCA1, could be a significant risk factor to other cancer forms as well." (PMID 38053165, 2023). "DNA repair deficiencies in cancers may result in characteristic mutational patterns, as exemplified by deficiency of BRCA1/2 and efficacy prediction for PARP inhibitors." (PMID 36883553, 2023). "Indeed, PARP inhibitors are widely used in the management of ovarian and breast cancers with BRCA1/2 mutations, but also in metastatic pancreatic cancer with BRCA1/2 mutations." (PMID 37760415, 2023). "This may be explained by diagnosis of BRCA cancers at a younger age, or an active medical follow-up in patients carrying BRCA1/2 mutations." (PMID 38152363, 2023). "The early onset of cancer suggests that the factors causing cancer in BRCA1 carriers might manifest before many women undergo RRO, influencing disease incidence." (PMID 38201529, 2023).
cancer (continued). "Although BRCA1/2 has been the focus for synthetic lethality, the loss of other vital proteins in the DNA repair and replication pathways has been shown to sensitize cancer cells to PARP inhibitors." (PMID 37508568, 2023). "However, there is now clinical evidence to support their use in other molecular subsets of cancers beyond HR-deficient BRCA1/2-mutant cancers or in combination with other targeted drugs to potentiate the clinical efficacy of modern cancer therapies." (PMID 37609662, 2023). "This review aims to give an overview about all available the studies in which psychological outcomes have been assessed in cancer-unaffected BRCA1/2 pathogenic variant carriers, whether as a primary outcome or secondary measurement." (PMID 37185387, 2023). "The OlympiA double-blinded, randomized Phase III trial was performed to determine if olaparib could reduce the rate of recurrence of cancers in individuals with BRCA1/2 mutations." (PMID 37035242, 2023). "Therefore, it motivated us to test the synthetic lethality of PSPC1 inhibition in BRCA1/2-mutated cancer." (PMID 38069409, 2023). "Four inhibitors of PARP (olaparib, talazoparib, rucaparib, and niraparib) have been approved for the treatment of cancers associated with BRCA1 and BRCA2 mutations as PARPi were found to be specifically lethal to BRCA1/2-deficient cells, following the principle of synthetic lethality." (PMID 37898399, 2023). "Taken together, these recent Phase II trials suggest that the BRCA1/2 mutated cancers may benefit from the combination approaches of PARP inhibitors and immunotherapy agents." (PMID 37035242, 2023). "It will be important to test whether inhibiting APE2 function via pharmacological inhibitor Celastrol can be used as a monotherapy of BRCA1/2-proficient or -deficient cancers." (PMID 36755963, 2023). "In the first instance, we assessed whether reversion mutations in BRCA1, the most clinically validated mechanism of PARPi and platinum salt resistance in BRCA1 mutant cancers, could explain the PARPi resistance in this individual." (PMID 37491606, 2023). "Among the younger group, 53 had BRCA1/2 germline PVs/LPVs (38%), 15 were carriers of other cancer susceptibility genes (10%), primarily APC, NBN, ATM, MUTYH, MLH1, and only 2 patients were carriers of PVs/LPVs in both BRCA1/2 and other susceptibility genes (1%)." (PMID 38136276, 2023). "However, the use of PARP inhibitors is most relevant for the treatment of cancers characterized by the presence of mutations within the BRCA1 and BRCA2 genes." (PMID 37886943, 2023). "However, the optimal sequencing of therapy remains an unanswered question for a subset of mTNBC patients who harbor germline breast cancer gene 1/2 (BRCA1/2; gBRCA1/2) mutation." (PMID 38213539, 2023). "Cancer cell resistance to PARPi might also occur through restoration of HR upon reactivation of BRCA1/2 function or loss of DNA end protection." (PMID 37686260, 2023). "Our study may be useful for genetic counseling and cancer risk evaluation for relatives of BRCA1/2 carriers in the Chinese population." (PMID 36861435, 2023). "We acknowledge that some BRCA1 cancers are responsive to Polθi, although loss of end resection factors could contribute." (PMID 38001070, 2023). "Hormonal replacement therapy significantly compensates for hormonal deprivation and counteracts menopausal syndrome morbidity and mortality; however, some data suggest a possible correlation between hormonal medications and cancer risk, especially in BRCA1\2 carriers who undergo long-term regimens." (PMID 36614207, 2023).
cancer (continued). "However, most cancer patients who are prescribed the PARP inhibitor have to have germline mutations in BRCA1/2 genes." (PMID 36794257, 2023). "Two variants in ATM and BRCA1 were identified in patients with a family history of cancer." (PMID 37234870, 2023). "If cancer cells harbor BRCA1/2 gene mutations and another DNA repair pathway is impeded by PARPase inhibitors, such as Olaparib, then both DNA repair pathways are blocked, leading to cancer cell death due to untimely DNA repair." (PMID 38352694, 2023). "Reduced BRCA1 expression is linked to both cancer and neurodegeneration." (PMID 37626783, 2023). "For high-risk cancer predisposition genes, such as BRCA1/2, the identification of founder variants in a certain population could help designing customized cost-effective cancer screening panels." (PMID 37400873, 2023). "The well-established dysregulation of miRNA expression in cancer, together with the contribution of miRNAs to tumorigenesis and the fact that in BRCA1/2 mutation carriers, the genetic alterations are present in all body cells, offers a probable explanation for a distinct circulating miRNA signature." (PMID 37291133, 2023). "While three patients with BRCA1 mutations had other subsequent cancers." (PMID 37386498, 2023). "These sporadic cancers share phenotypic overlap with BRCA1/2 germline-mutated tumors." (PMID 36769287, 2023). "In future perspective, it would be valuable to investigate whether the tested PRS also contribute to the risk of developing secondary cancer in BRCA1 PV carriers." (PMID 37296919, 2023). "Some CPGs predispose to multiple primary cancer types, such as BRCA1 with OC and BC, although there is often a preferential predisposition to certain histological subtypes such as the association of BRCA1 with HGSC." (PMID 36833203, 2023). "Several factors such as genetics, for example, BRCA1 gene mutations, may predict multiple primary cancers." (PMID 37829945, 2023). "PVs and LPVs in BRCA1/2 genes cover a percentage ranging from 20 to 25% of all hereditary breast cancers (BCs) and about 5–10% of all BCs and are correlated to an increased risk of developing some types of aggressive carcinomas." (PMID 37046793, 2023). "As evidenced by CRISPR/Cas9, the germline mutations in the BRCA1 gene could be overcome through somatic alternative splicing, leading to therapeutic resistance to cancer." (PMID 35879772, 2022). "Thus, BRCA1- or BRCA2-mutated cancer cells exhibit an increased sensitivity to PARP inhibitors when compared to normal cells." (PMID 35328658, 2022). "We found daily levels of progesterone to be higher throughout the menstrual cycle of BRCA1/2 mutation carriers, implying progesterone signalling may be targeted for cancer risk reduction in this population." (PMID 35701800, 2022). "However, the advances in cancer genomes, specifically the impact of germline and somatic mutations of BRCA1/2 and the effacy of PARPi in PCa have shifted the treatment paradigm." (PMID 36230674, 2022). "To better explore the reason behind the gap between the high prevalence of symptoms and the low treatment uptake, we asked whether they believed that HRT had an effect on BRCA1/2-related cancer risk." (PMID 35884518, 2022). "The early oncogenic effects of Brca1 mutation highlights that cancer prevention in human BRCA1 mutation carriers may need to start earlier than current practice in order to effectively disrupt the oncogenic process." (PMID 35869059, 2022). "However, our study contains an indirect independent validation because it suggests that there is an association between BRCA1 methylation and TNBC and HGSOC, the 2 cancer forms most strongly associated with germline BRCA1 pathogenic variants." (PMID 36074460, 2022).
cancer (continued). "Our study revealed that heterozygotic Brca1 mutation alone can cause genome instability at embryonic stage, highlighting that prevention of BRCA1 mutation-related cancer in humans may need to start earlier than currently considered." (PMID 35869059, 2022). "BRCA1 PVs were associated with risks of male breast (RR = 4.30; 95% CI, 1.09 to 16.96), pancreatic (RR = 2.36; 95% CI, 1.51 to 3.68), and stomach (RR = 2.17; 95% CI, 1.25 to 3.77) cancers." (PMID 35077220, 2022). "Studies indicate that the high risk of cancer in BRCA1/2 germline mutation carriers may be mitigated by physical activity, especially during adolescence and early adulthood." (PMID 35190584, 2022). "Moreover, some PARP suppressors are effective as single agents against cancers bearing BRCA1- or BRCA2-mutations." (PMID 35956876, 2022). "Given that SF3B1 is the most highly mutated member of this complex in a variety of cancers, we hypothesized that loss or mutation of this subunit would result in a DNA repair defect akin to what is observed in BRCA1-mutant tumors." (PMID 35027467, 2022). "40–60 year old BRCA1 carrier men’s cancer risk is twice that of men in general population." (PMID 35469032, 2022). "Due to the close relationship between cancer and BRCA1 and 2 mutations, it is important to evaluate whether the cancer itself or the BRCA mutations underlie the reduced ovarian reserve in these women." (PMID 35626104, 2022). "The enhanced effect on cAMP production in the BRCA1-deficient cancer cells may be due to the overexpression of ADRB1." (PMID 35517499, 2022). "Moreover, cancers arising from the fallopian tubes (about 70%) and high-grade serous cancers are usually associated with BRCA1/2 mutations." (PMID 35645374, 2022). "We reasoned that by dynamically monitoring genome status in BRCA1 mutation carriers during the developmental process before cancer development, we would be able to test our hypothesis." (PMID 35869059, 2022). "The variants in panel genes, HRR (homologous recombination repair)-related genes, and BRCA1/2 were significantly associated with the following clinicopathological factors: age at the initial diagnosis of BC, family history of any cancer, molecular subtype, Ki-67 index, and hereditary risk." (PMID 36232564, 2022). "Therefore, HR-deficient cancer cells (e.g., BRCA1 or BRCA2 mutated) are hypersensitive to PARP inhibition." (PMID 35349716, 2022). "Patients with BRCA1 mutations have a higher risk for cancer." (PMID 35300412, 2022). "BRCA1/2 mutations frequently indicate a deficiency in repairing DNA DSBs by homologous recombination and predispose patients to breast, ovarian, and other cancers." (PMID 36209184, 2022). "Inherited cancer predisposition could be related to BRCA1 or BRCA2 mutations in 21.4% of the 524 probands, a proportion that increases to 28.9% of the families with an a priori BRCAPRO mutation probability >10%." (PMID 36230639, 2022). "The activity of PARPi in certain cancers with deficient homologous recombination repair ability (mainly due to BRCA1/2 mutations) was the first clinical demonstration of the role of exploiting HR alterations to improve outcomes and prolong survival in cancer patients." (PMID 36358724, 2022). "In addition, resistance to PARP inhibitor of BRCA1/2 mutated cancer is due to the lowered activity of endogenous PARG." (PMID 35447104, 2022). "Another group asked whether SGE data predicted BRCA1-related cancer risk in an unbiased cohort of over 92,000 individuals." (PMID 38836089, 2022). "Tubo-ovarian cancer (TOC) is a sentinel cancer for BRCA1 and BRCA2 pathogenic variants (PVs)." (PMID 35263119, 2022). "Whether this also applies to cancer-affected BRCA1/2 mutation carriers and has an influence on the VO2peak still needs to be investigated." (PMID 35190584, 2022). "Interestingly, results of a Phase I trial of CX-5461 have published very recently showing a 14% partial responses in female patients with cancers with mutations of BRCA1/2 or PALB2 genes." (PMID 36114513, 2022).